KRT14 (keratin 14)
Diseases named in the same sentence as KRT14 in open-access papers (continued):
Sharing a sentence is not in itself a finding about the gene and the disease.
bladder cancer (26 papers, 2016 to 2025). "A similar response was demonstrated in bladder cancer, in vivo, where KRT14+ LC bladder cancer cells were resistant to combined gemcitabine and cisplatin treatment." (PMID 39408880, 2024). "These stages of differentiation also occur in bladder cancers with KRT14 expressed in the least differentiated bladder cancer and KRT20 expressed in the highly differentiated bladder cancers." (PMID 36293167, 2022). "Increased expression of KRT14 is negatively associated with progression-free survival and response to therapy in ovarian cancer patients, and KRT14+ cells are also enriched in chemo-resistant bladder cancer." (PMID 34470672, 2021). "In humans, Krt14 expression characterises undifferentiated bladder cancers with particularly poor prognoses." (PMID 33630958, 2021). "Rodent bladder cancer models indicate that a significant proportion of cancerous tissue derives from Krt14 positive cells." (PMID 33630958, 2021). "Using a combination of the two drugs, several proteins associated with the basal subtype of bladder cancers were consistently decreased within both cell lines such as KRT1, KRT14, KRT16, P63, and TFAP2A." (PMID 32822399, 2020). "And also metformin represses bladder cancer CSC repopulation evidenced by reducing cytokeratin 14 (CK14+) and octamer-binding transcription factor 3/4 (OCT3/4+) cells in both animal and cellular models." (PMID 27058422, 2016). "AldeFluor activity was linked to tumor-initiating cells in bladder cancer in a previous publication, but the authors did not investigate the association with KRT14 expression." (PMID 32326336, 2020). "However, a combined treatment of TG and PD resulted in a consistent decrease of several proteins associated with the basal subtype of bladder cancers (KRT1, KRT14, KRT16, P63, and TFAP2A)." (PMID 32822399, 2020). "It is tempting to conjecture that the enrichment of KRT14-expressing cells may occur over time, following repeated rounds of chemotherapy; indeed, the chemo-enrichment of KRT14+ cells has been reported in bladder cancers." (PMID 31443478, 2019). "Similar to breast and bladder cancers, our data indicate that KRT14 expression may also mark the LC population in OCs." (PMID 31443478, 2019). "The expression of KRT14 is seen in the least of the differentiated tumors and its expression correlates to poor prognosis KRT14, whereas the expression of KRT20 is restricted to differentiated bladder cancers and its expression is associated with good prognosis." (PMID 32822399, 2020). "The decrease in the expression of KRT14 in the UROtsa parent and transformed cells suggests that the activation of PPARγ or inhibition of cell proliferation may decrease the regenerative capacity of the normal urothelium as well as bladder cancers." (PMID 32822399, 2020). "Cytokeratin 14 (KRT-14), aldehyde dehydrogenase 1a (ALDH1a), and the transcription factors SOX2 and CD44 have been shown to initiate bladder cancer." (PMID 38607066, 2024). "The same study found TRIM29 gene expression to be correlated to KRT5, KRT14, KRT6A, and KRT16 expression using The Cancer Genome Atlas (TCGA) RNA sequencing data from multiple tumor types, including basal subtype bladder cancers." (PMID 32822399, 2020). "Keratin 14 (K14), which contains a nonhelical tail domain involved in K5–K14 large bundles self‐organising, has been shown to be overly expressed in basal‐like bladder cancer, and K14+ cell subpopulations serving as bladder cancer stem cells contribute to tumourigenesis and chemoresistance in vivo." (PMID 35522942, 2022).
breast tumors (24 papers, 2008 to 2024). "In some breast tumors, a population of cancer cells (basal-like cells) maintain several epithelial characteristics and express the myoepithelial/basal cell marker Keratin 14 (K14)." (PMID 38849373, 2024). "To further explore whether SOX4 is required for regulating differentiation of PyMT breast tumors we analyzed expression of the luminal marker Keratin 8 (K8) and the basal marker Keratin 14 (K14)." (PMID 34584219, 2021). "Cytokeratin-14 (K14) has recently been recognized as a marker for highly migratory cancer cells in breast tumors that can initiate collective invasion, a critical step during metastatic progression of breast tumors." (PMID 30898152, 2019). "All analyzed tumors were found to be ERα-negative, negative for or weakly expressing keratin 8, and keratin 14-positive, similar to breast tumors that tend to arise in carriers of BRCA1 pathological variants." (PMID 35393420, 2022). "In breast tumor cells, DDR2 regulates tumor cell collective invasion by sustaining a SNAIL1 (SNAI1)-mediated epithelial–mesenchymal transition (EMT) invasive program, particularly in keratin 14 (KRT14)-positive leader cells, as well as full activation of collagen-binding integrins." (PMID 34477203, 2021).
melanoma (23 papers, 2008 to 2025). A malignant, usually aggressive tumor composed of atypical, neoplastic melanocytes. "We noted an increase in the number of melanomas in the heterozygous KRT14-Cre/TRIM16+/flox mice, compared to other genotypes, at 15 weeks (*P = 0.0129)." (PMID 31342168, 2019). "It was reported that KRT14 potentially facilitates melanoma tumorigenesis." (PMID 35054979, 2022). "Increased expression of KRT6B, KRT14, and KRT17 was associated with poor survival in melanoma." (PMID 36553569, 2022). "In our study, high expression of KRT14 is closely related to tumor stage and poor prognosis in melanoma patients, which may provide new clues for the diagnosis and treatment of malignant melanoma." (PMID 33441834, 2021). "Presence of melanoma likely influences the differentiation pattern of epidermis with highly aberrant suprabasal pattern of expression of differentiation-dependent marker keratin 14 (K14), which is normally present only in basal cell layer." (PMID 25560632, 2015). "We defined clusters corresponding to melanoma (PMEL, MLANA), immune infiltrates (TRBC2, TRAC, TMSB4X), melanophages (CD74, LYZ), keratinocytes (KRT14, TRIM29), blood vessels (CAVIN1, PECAM), and fibroblast‐enriched areas in the dermis (DCN, COL1A2, FBLN1)." (PMID 39846232, 2025). "Among these hub genes, we identified the attenuated expressions of CDH1, COL17A1, DSG1, KRT14, and FLG in melanoma metastases compared with primary melanoma via bioinformatics analysis upon the GSE8401 and TCGA datasets." (PMID 35054979, 2022). "Initially, we plotted the expression of three genes which are tightly restricted to the keratinocyte lineage (IVL, KRT14 and BNC) for the 473 melanoma samples within the TCGA RNA sequencing dataset." (PMID 27340778, 2016). "Genes such as KRT14, GJA1, S100A7, S100A9, and EHF were higher in most melanomas while genes such as CITED-1, GDF15, QPRT, OCA2, c-MET and MME were more highly expressed in NHEM." (PMID 18442402, 2008). "Cells re-isolated from OS-REp via trypsin were positive for the keratinocyte marker cytokeratin 14 and negative for the melanoma marker Melan-A." (PMID 36175453, 2022). "Cg-Tg (KRT14-Kitl*) 4XTG2Bjl/J mice, which express mutant mouse Kitl cDNA and possess abundant melanocytes in the epidermis, as well as the xenograft tumors of B16 and B16F10 mouse melanoma cells implanted in C57BL/6 mice." (PMID 32968045, 2020). "The K14-SCF mouse model, which expresses stem cell factor (SCF) in epidermal keratinocytes under control of the keratin 14 promoter, also exhibits retention of melanocytes in the interfollicular layer of skin yet is melanoma-resistant." (PMID 28788083, 2017). "This set of genes included forkhead box C1 (FOXC1), keratin 14 (KRT14), cyclin E1 (CCNE1), melanoma inhibitory activity (MIA) and secreted frizzled-related protein 1 (SFRP1), while expression of CDCA1 and MELK, (neither of which were detectable in MCF7), did not change following SOX11 depletion." (PMID 26894864, 2016). "This study reveals the genes C7, MMP3, KRT14, LOC642587, CASP7, S100A7 and miRNAs hsa-mir-205 and hsa-mir-203b as the key genomic features that may substantially contribute to the oncogenesis of melanoma." (PMID 31673075, 2019). "Genes, such as members of the keratin family (KRT17, KRTDAP, KRT6B, KRT14, KRTAP13-2) are expressed more in primary tumor, possibly indicating the differentiated status of less advanced cancers, or this could be a disruption in their normal expression by melanoma processes." (PMID 36553569, 2022).
papilloma (22 papers, 2005 to 2023). A benign epithelial neoplasm that projects above the surrounding epithelial surface and consists of villous or arborescent outgrowths of fibrovascular stroma. "Compared with those in the control mice, the papillomas in Mcpip1eKO mice showed increased expression levels of KRT14; in contrast, KRT10 expression was clearly reduced." (PMID 34903245, 2021). "Mcpip1eKO papillomas were characterized by elevated transcriptional expression of Krt5, Krt13 and keratin 14 (Krt14), indicating a highly proliferative phenotype." (PMID 34903245, 2021). "Papillomas induced by the wild type and E7D90A quasiviruses also showed similar patterns of keratinocyte differentiation, with cytokeratin 14 upregulated in the suprabasal layers of the papillomas, indicating similar delays in terminal differentiation." (PMID 34465025, 2021). "Immunohistochemical analysis of differentiation layer markers cytokeratin 14 (K14) and cytokeratin 10 (K10) was used to assess the differentiation state of papillomas in comparison with normal uninfected skin." (PMID 28107544, 2017). "Keratin 14 was diffusely expressed in the epidermis and hair follicles in the areas of hyperplasia and throughout both papillomas and trichoblastomas." (PMID 25474466, 2014). "Transgenic mice that overexpress PKCδ in the basal layer via a keratin 14 (K14) promoter are resistant to standard two-stage skin tumorigenesis in that they develop significantly fewer number of papillomas and carcinomas." (PMID 21297902, 2010). "Sections of typical papillomas were analyzed by immunofluorescence for differentiation markers including Keratin 14, 10 and Loricrin." (PMID 21042537, 2010). "Staining skin specimens with H&E or anti-keratin 14 indicated that the tumors were derived from keratinocytes and possessed characteristics of papillomas." (PMID 20334655, 2010). "Using a lineage-labeling system driven by Keratin 14 (K14)-CreER, which marks basal epithelial cells within the epidermis, the authors found that only 20% of these cells are capable of generating a large clonal population of pre-malignant papilloma cells." (PMID 26839398, 2016). "The increased expression of KRT14, accompanied by reduced expression of KRT10, in the Mcpip1eKO papillomas indicated the acquisition of a more aggressive phenotype." (PMID 34903245, 2021). "When expressed in transgenic mice under the control of the keratin-14 promoter (K14-HPV8-E6), HPV8-E6 induces the development of papillomas - partially with moderate to severe dysplasia and SCC." (PMID 30344928, 2018). "Mice expressing the complete early region of HPV-8 under the control of the keratin 14 (K14) promoter show spontaneous skin papilloma development from the age of 14 weeks and therefore provide a unique model to study HPV-8 induced papilloma formation." (PMID 27506937, 2016).
dermatitis (20 papers, 2009 to 2025). An inflammatory process affecting the skin. "In the present study, we assess the risk of mortality in septic conditions, its pathogenesis, and its underlying causes using a mouse dermatitis model: KCASP1Tg mice, which overexpress keratin 14-driven caspase-1." (PMID 38203647, 2023). "In this study, we examined the potential causes and pathogenesis of increased sepsis susceptibility in inflammatory skin diseases using a mouse dermatitis model: keratin 14-driven caspase-1 is overexpressed (KCASP1Tg) in mice on a high-fat diet." (PMID 38203647, 2023). "BALB-CMV Sharpin-/-, B6-CMV Sharpin-/-, and Krt14 Sharpin-/- mutant mice developed extensive dermatitis similar to the two spontaneous allelic null mutations, Sharpincpdm/cpdm and Sharpincpdm-Dem/cpdm-Dem with no sexual dimorphism." (PMID 32687504, 2020). "Remarkably, selective deletion of Sharpin in keratinocytes is sufficient to recapitulate the dermatitis of mice with the spontaneous Sharpin mutation, and this was associated with a marked increase of serum IgE as the B cells in Krt14 Sharpin-/- mice were able to undergo isotype switching." (PMID 32687504, 2020). "To evaluate the psychological symptoms of uncontrolled dermatitis, we conducted an experimental behavioral analysis using a mouse model of spontaneous dermatitis, keratin 14-driven caspase-1 overexpressing (KCASP1Tg) mice." (PMID 36983014, 2023). "We addressed this problem using keratin 14-specific caspase-1 overexpressing transgenic (KCASP1Tg) mice with severe erosive dermatitis from 8 weeks of age, followed by re-epithelization." (PMID 32397568, 2020). "We addressed this problem by using keratin 14-specific human caspase-1 overexpressing transgenic (KCASP1Tg) mice, which are accepted as a spontaneous dermatitis model." (PMID 32397568, 2020). "The concentration increased with the age of the mice and the progression of the dermatitis, and was much higher in the Krt14 Sharpin-/- mice than the other mutant strains." (PMID 32687504, 2020). "Therefore, we evaluated the influence of skin inflammation on sperm dysfunction in an acute spontaneous dermatitis mice model, keratin 14-specific human caspase-1-overexpressing transgenic (KCASP1Tg) mice." (PMID 32825298, 2020). "We observed that the control mice (Krt14+/+-Mlklflox/flox) presented similar dermatitis lesions as wild type mice, but we did not observe dermatitis skin appearances in Mlkl cKO mice (Krt14Cre/+-Mlklflox/flox)." (PMID 36344541, 2022).
skin tumors (18 papers, 2008 to 2026). "In mice expressing the complete early region of HPV8 under the keratin 14 (K14) promoter even spontaneous development of skin cancers was observed." (PMID 29563902, 2018). "To further elucidate the tumorigenesis of MEK2 in zebrafish, we established a transgenic zebrafish known as Tg(krt14:MEK2S219D-GFP) in which expression of the MEK2S219D-GFP fusion protein was driven by the krt14 promoter to establish a skin tumor animal model." (PMID 26572230, 2015). "Histologic analysis and staining for Involucrin, Cytokeratin-14 and β-Catenin revealed that these skin tumors were all malignant SCC." (PMID 25329316, 2014). "Experiments using transgenic mice expressing Potorous tridactylus CPD-photolyase under the control of the keratin-14 promoter (K14-CPD-PL) indicated that fast removal of CPDs from K14-permissive cells dramatically decreased the incidence of skin cancer in UV-treated animals." (PMID 26511842, 2015). "As the KRT14-Cre; NCT system predominantly initiates tumors in the oral cavity, tumor burden on this site often impairs drinking, feeding, and breathing before skin tumors become externally detectable or measurable." (PMID 41266112, 2026). "We established a constitutive MEK2 transgenic zebrafish, Tg(krt14:MEK2S219D-GFP), to elucidate the role of MEK2 in skin tumor formation." (PMID 26572230, 2015). "Moreover, a mouse skin tumor model where cells expressed 4-hydroxytamoxifen-regulated ROCK, which consists of ROCK kinase domain and estrogen receptor under control of cytokeratin 14 promoter, revealed a relationship between ROCK-induced cytoskeletal rearrangement and tumor progression." (PMID 27203208, 2016).
ovarian carcinoma (14 papers, 2008 to 2024). A malignant neoplasm originating from the surface ovarian epithelium. "Loss of KRT14+ cells diminished the invasive capacity of ovarian cancer spheroids, suggesting a potential role of E/M KRT14 + cells in peritoneal invasion." (PMID 34001250, 2021). "Our data demonstrate KRT14 cells as an ovarian cancer “leader cell” phenotype underlying tumor invasion, and suggest their importance as a clinically relevant target in directed anti-tumour therapies." (PMID 31443478, 2019). "Moreover, we demonstrated increased KRT14 expression is negatively associated with progression-free survival and response to therapy in ovarian cancer patients." (PMID 34470672, 2021). "KRT14+ LCs also localise to the outer edges of ovarian cancer spheroids in a similar manner and mediate attachment to and invasion of the mesothelium with KRT14 expression restricted to cancer cells at the invasive interface." (PMID 39408880, 2024). "Ovarian cancer patients with high KRT14 expression have reduced progression-free survival following standard-of-care platinum and taxane-based chemotherapy (HR 1.27; 95% CI 1.07–1.51 p < 0.006)." (PMID 39408880, 2024). "Enrichment of KRT14 expression has also been demonstrated in matched tumour tissues from ovarian cancer patients pre- and post-neo-adjuvant chemotherapy." (PMID 39408880, 2024). "Ovarian cancer leader cells displayed enriched expression of KRT14 and TWIST-1 but expression levels of N-cadherin, vimentin, Slug, and Snail remained identical to FCs." (PMID 39408880, 2024). "Our own studies have shown KRT14 expression is confined to the leading edge of ovarian cancer cells in both 2D and 3D format with KRT14 ablation rendering ovarian cancer cells invasion incompetent." (PMID 30909510, 2019). "Single-cell sorting of individual leader (KRT14+) and follower (KRT14−) ovarian cancer cells demonstrated that each gave rise to a mixed leader–follower population that maintained the same proportions of LCs as the initial line from which the cells were derived." (PMID 39408880, 2024). "implicated the basal epithelial marker KRT14 as an absolute determinant for ovarian cancer cells’ spheroid integrity, mesothelial attachment, invasive potential, and chemotherapy resistance, which could provide some in vitro evidences to explain the role KRT14 plays in cancer." (PMID 36998462, 2023). "Keratin-14 (KRT14)-positive leader cells mediate mesothelial clearance and invasion by ovarian cancer cells." (PMID 36212119, 2022). "To facilitate studies of the LC subset in ovarian cancer, we used CRISPR to insert a bicistronic T2A-GFP cassette under the control of the native KRT14 promoter." (PMID 34470672, 2021). "Nevertheless, LCs gave rise to both KRT14+ and KRT14− daughter cells, indicating that LCs may exist as a non-terminally differentiated phenotype in ovarian cancer." (PMID 34470672, 2021).
Hyperkeratosis (12 papers, 2010 to 2025). Hyperkeratosis is a histopathological term defining a thickened stratum corneum and may be present in many different skin conditions, with many possible overlaps. "The epidermis of Krt14 Sharpin-/- mice contained numerous apoptotic keratinocytes and had marked acanthosis and ortho- and parakeratotic hyperkeratosis resulting in a significant increase of epidermal thickness." (PMID 32687504, 2020). "Interestingly, we found that after treatment with QBX258, these pathological changes improved in the lymphedematous limb, and, for the most part, returned to normal levels noted in the unaffected limb (hyperkeratosis, p < 0.01; Ki67+ cells, p < 0.05; KRT14 p < 0.001)." (PMID 34571811, 2021). "Given the hyperkeratosis observed in VDR-KO rats through HE staining, we conducted Western blotting using the antibody against the keratin marker Krt14 and anti-pan-keratin antibody (PCK26), which detects rat keratin 1 (66 kDa), keratin 5 (58 kDa), and keratin 8 (52 kDa)." (PMID 39796272, 2025). "Unlike our COL7A1 patient, our KRT14 patient had extensive palmar and plantar hyperkeratosis." (PMID 38580989, 2024).